IGF1 (insulin like growth factor 1)
Diseases named in the same sentence as IGF1 in open-access papers (continued):
Sharing a sentence is not in itself a finding about the gene and the disease.
tumor (continued). "Under CSF-1R inhibition, the tumor microenvironment drives treatment resistance via stimulation of the PI3K signaling caused by tumor cell IGF-1 receptor (IGF-1R) and macrophage-derived insulin-like growth factor-1 (IGF-1)." (PMID 37012233, 2023). "Elevated insulin levels indirectly or directly promote tumor cell proliferation and reduce apoptosis through the production of other hormones, such as insulin-like growth factor (IGF-1)." (PMID 37940857, 2023). "The role of IGF-1 signaling in controlling rates of cell renewal has led to an interest in the relevance of this regulatory system to neoplasia." (PMID 36831629, 2023). "In this study, we aimed to determine the circulating levels of IGF-1, IGFBP-2, and IGFBP-3 in patients with CRC and to investigate their association with different clinical aspects of CRC, including risk, tumor grade, and tumor stage." (PMID 38137390, 2023). "The removal of the tumor not only releases normal pituitary tissue from compression of tumor tissue, but it also retains normal pituitary function by removing excess GH and IGF-1 in the subject’s blood that affects FSH/LH secretion." (PMID 37886642, 2023). "If IGF-1 is elevated or the GH suppression test is positive, these findings should prompt imaging studies to localize the GH-secreting tumor." (PMID 37755395, 2023). "Factors such as patient biometrics, duration of disease, SAGIT score, tumor size, GH, insulin-like growth factor 1 (IGF-1), calcium, phosphorus, parathormone, and vitamin D were analyzed concerning current disease status (naïve, non-remission, remission)." (PMID 38137499, 2023). "Responder patients were older and presented lower basal GH and IGF1 concentrations and lower tumor diameter." (PMID 38027102, 2023). "Somatostatin analogs have proven effective in suppressing GH secretion by the pituitary gland and pituitary adenomas, as well as efficacy in suppressing hepatocyte IGF-1 production and in arresting tumor growth." (PMID 37755395, 2023). "Of the few studies reporting long-term follow-up data exceeding three years postoperatively, preoperative GH and IGF-1 levels, tumor size and invasiveness, and age at diagnosis were among factors predicting long-term biochemical control after surgery." (PMID 37665404, 2023). "After the addition of cactus extract, the mRNA expression of VEGF and IGF-1 decreased, which helped to prevent tumor proliferation and swelling." (PMID 36627306, 2023). "The influence on the prognosis of factors such as the tumor size and preoperative levels of GH and IGF-1 is also quantified." (PMID 36335516, 2023). "In contrast to serum IGF-1, the intraprostatic expression of IGF-1 has a more consistent association with tumor grade, pathological stage, and disease progression." (PMID 36831629, 2023). "IGF-1 expression level is reported to increase in tumor cells, which can promote tumor occurrence through the promotion of cell proliferation or inhibition of cell apoptosis." (PMID 37372393, 2023). "Tumor cells as well as cardiac cells can act as endocrine organs by releasing or affecting the release of hormonal signals such as insulin, IGF‐1, growth hormone, as well as inflammatory cytokines." (PMID 37654192, 2023). "Further, increased levels of IGF-1 has been associated with increased risk for several malignancies, and studies have suggested GH and IGF-1 to facilitate a tumor microenvironment and neoplastic growth in the colon." (PMID 36525222, 2023).
tumor (continued). "Multiple agents targeting IGF-1/IGF-1R signaling have shown effects against tumor growth in tumor xenograft models, but further verification of their effectiveness in PCa patients in clinical trials is still needed." (PMID 36831629, 2023). "GH and IGF1 promote cell proliferation, with a potential contribution to carcinogenesis and tumor progression." (PMID 37373068, 2023). "We identified two mechanisms through which the fasting-induced reduction in insulin, IGF1 and leptin cooperates with CBIs to lower intratumour cholesterol and to slow tumour growth." (PMID 37907500, 2023). "In fact, it has been demonstrated that IGF-1 influences tumor growth, having a mitogenic and antiapoptotic role." (PMID 37746082, 2023). "This involved analyzing the gene expression of CTLA-4 and serum levels IGF-1 in peripheral blood cells and sera to detect the tumor's responsiveness to the targeted therapy trastuzumab." (PMID 38406785, 2023). "In contrast, IGF1R activation in tumor cells is strictly dependent on Sdc1, even if IGF1 is present, and is therefore blocked by SSTNIGF1R." (PMID 36968227, 2023). "Tumor- and stromal-derived IGF-1 stimulates signaling, which increases cell proliferation and survival while reducing apoptosis." (PMID 37373743, 2023). "Circulating levels of IGF-1, IGFBP-2, and IGFBP-3 were investigated for their association with tumor grade and stage." (PMID 38137390, 2023). "Subgroup analysis suggested trends towards benefit with Xe1000 + En160 in patients whose tumours had high levels of IGF1 mRNA or PTEN protein." (PMID 37537253, 2023). "Sparse tumor GNPs transdifferentiate into TuAstrocytes, which secrete IL-4 to polarize microglia and induce IGF1 secretion, which is critical for tumor progression." (PMID 37705736, 2023). "CRC cell lines isolated from a primary tumor site showed higher IGF-1 expression among other growth factors and proangiogenic factors compared to metastatic cell lines." (PMID 36835075, 2023). "Insulin levels increase insulin-like growth factor-1 (IGF-1) activity, important in tumour initiation and progression, and is associated with increased oestrogen bioavailability, which promotes breast carcinogenesis." (PMID 36737658, 2023). "Our scRNAseq data confirmed increased expression of IGF-1 among clonal tumor cells post-vaccine in both plasma cell-like clusters (clusters 5 and 10) but not in any B-cell clusters (0, 1, and 2)." (PMID 37790486, 2023). "In general, the effects of αKlotho are beneficial: Also by inhibiting insulin-like-growth factor 1 (IGF-1) or Wnt signaling, αKlotho exerts anti-tumor effects." (PMID 36967770, 2023). "By using RNA−Seq data of CRC patients from The Cancer Genome Atlas (TCGA) database, we divided the patients into normal group(58 patients)and tumor group(446 patients), and analyzed the expression and prognostic value analysis of IGF-1,IGF1R and RAGE." (PMID 36890832, 2023). ""S" component correlated with IGF-1 concentrations (p < 0.0001, r = 0.263), glucose levels (p = 0.005, r = 0.158), time from diagnosis (p = 0.0039, r = − 0.165), and tumor size (p = 0.0001, r = 0.226)." (PMID 36841880, 2023). "A potential explanation can be found in the contextual and stage-related expression pattern of IGF1 versus IGF2 at the focal tissue level (tumor microenvironment)." (PMID 38255147, 2023). "HCP5 facilitates cell proliferation and restrains apoptosis via miR-27a-3p/IGF-1 axis in human granulosa-like tumor cell line KGN." (PMID 36917093, 2023). "In agreement with these functions, our MPM AFs showed increased expression of IL-6, IL-17A, PDGFs, various FGFs and IGF-1, all molecules reported to improve the survival and chemoresistance of tumour cells through their cross-talk with CAFs." (PMID 37938546, 2023). "Continued research into the precise interactions of IGF-1 signaling and autophagy is important, mainly with respect to new anti-inflammatory and anti-tumor therapies, especially for patients with MetS." (PMID 36835075, 2023).
tumor (continued). "IGF-1R can be phosphorylated by its ligand or autophosphorylated, subsequently being rapidly internalized to mediate IGF-1-induced signaling that promotes tumor cell growth and proliferation." (PMID 36831629, 2023). "The insulin-like growth factor 1 (IGF1) and insulin pathway are both involved in tumor proliferation and progression." (PMID 38136416, 2023). "Hyperactivation of 5-HT7 in the liver leads to secretion of the growth factor IGF-1, which accelerates proliferation of metastatic tumour cells." (PMID 36768393, 2023). "In the same work, they also demonstrated that circulating insulin-like growth factor 1 (IGF1) had a critical role in maintaining tumour phenotype and survival of already transformed Pheo cells in vivo." (PMID 37033265, 2023). "Animal tumor models show that IGF-1 is involved in OS pathogenesis and metastatic behavior, although this relationship has not been clearly established." (PMID 37176035, 2023). "The group receiving IF alone or in combination with TQ had the lowest serum IGF-1 levels for all the tumor-bearing mice (p < 0.05)." (PMID 38202341, 2023). "Firstly, we performed a univariate logistic regression analysis model considering GH and IGF-1 preoperative levels, tumor volume, reoperation, the signal on T2-weighted MRI, gender, and modified Knosp grade." (PMID 37364152, 2023). "Taken together, these clinical findings supported the interplay between YAP and IGF-1/IGF-1R pathway in tumor progression." (PMID 37081542, 2023). "The preoperative variables included age, gender, BMI, treatment history (surgery, medication and radiotherapy), MRI features (tumor dimensions, Knosp classification and clivus invasiveness), serum random GH and serum IGF-1 levels." (PMID 37371013, 2023). "A recent study found that the neutrophil-associated serine protease Cathepsin G can enhance the cell adhesion of E-cadherin by activating insulin-like growth factor 1, facilitating tumor cell aggregation, and aiding tumor cells in penetrating blood vessels." (PMID 37359527, 2023). "But the most important finding in our study is that the NEDD4 targeted strategy can only efficiently inhibit tumor growth in the IGF1 signaling-driven GC." (PMID 36774408, 2023). "Using a genetic mouse model, the CSF-1R inhibitor BLZ945 caused an acquired resistance via increased macrophage-derived insulin-like growth factor-1 (IGF-1) and tumour cell IGF-1 receptors, ultimately enhancing the PI3K pathway." (PMID 37686652, 2023). "There have been contradictory results regarding the relationship between PCa tumor grade and circulating IGF-1 levels from different studies." (PMID 36831629, 2023). "The results indicated that high-level IGF1 and IRS1 expression in GC is significantly associated with a more aggressive tumor phenotype." (PMID 36774408, 2023). "We have previously shown that tumor-associated myeloid cells provide critical support for T-ALL, in part by secreting IGF1 to activate IGF1R signaling in leukemic cells." (PMID 37805579, 2023). "The effect of vitamin D on the G1/S cell cycle transition is opposite to that of IGF-1 and also has antagonistic effects on angiogenesis and the tumor microenvironment." (PMID 37266156, 2023). "It is accurate to say that increased levels of insulin, IGF-1, and IGF-2 in the blood circulation are directly linked to the onset and spread of the majority of tumours." (PMID 36890832, 2023). "In CRC, the effects of the complex interactions of autophagy and IGF-1/IGF-1R signaling are expressed more clearly at the stage of tumor progression, in neoplastically transformed cells." (PMID 36835075, 2023). "Analysis of reverse interactions (i.e., stromal cells expressing ligand to a tumor receptor), revealed a potential interaction mediated by fibroblasts Insulin-like Growth Factor (IGF1) stimulating tumor cell IGF1 receptor." (PMID 36750562, 2023).
tumor (continued). "Although a reduction in IGF-1 is thought to be a leading candidate explaining fasting-induced tumor immunogenicity and improved therapeutic response, there are other possible mechanisms." (PMID 35186923, 2022). "Further studies examining the relationship between ghrelin, the GH/IGF-1 axis, and tumor growth are needed to clarify these interactions." (PMID 35454071, 2022). "IGF-1 stimulates the production of vascular endothelial growth factor, which promotes tumor development." (PMID 36138391, 2022). "IGF-1 from tumor-initiating cells can prevent miR-122 expression in neighboring normal hepatocytes and thereby facilitate its intercellular transfer within exosomes, leading to low levels of antiproliferative miRNAs in hepatic cancer cells." (PMID 36062186, 2022). "The modulation of both VEGF expression and tumor angiogenesis is also driven by molecules belonging to HIF1α and insulin-like growth factor 1 (IGF1)/insulin-like growth factor 1 receptor (IGF1R) signaling." (PMID 36432658, 2022). "We review data supporting the notion that tumor microenvironment mediates tumorigenesis partly through IGF-1 signaling pathway." (PMID 36017326, 2022). "IGF-1, BMI, and tumor size also contributed with less etiologic fraction and were adjusting factors." (PMID 36187107, 2022). "High levels of insulin and insulin-like growth factor (IGF)-1, expressed under the action of carbohydrate-rich food, can contribute to the proliferation of tumor cells through the insulin signaling pathway/IGF1." (PMID 35625744, 2022). "Treating A549 LUAD cells with IGF1, prevents tumor cell death, induces SLUG expression and stimulates cell migration." (PMID 35574343, 2022). "The peak GH response to GHRP-2 significantly and negatively correlated with BMI, serum creatinine levels, and tumor size while positively correlating with eGFR, serum IGF-1 level, and IGF-SD score." (PMID 35452483, 2022). "As in humans, some biomarkers have been shown to promote tumor development in animal models, such as an increase in the concentrations of IGF-1, leptin, and sex hormones and a decrease in the concentration of adiponectin." (PMID 36262532, 2022). "An immunofluorescent analysis showed that TGF-β1 and IGF-1 upregulate the expression of other adhesion-associated molecules, such as ICAM-1 and vimentin, on the surface of ascites-treated tumor cells and peritoneal cells." (PMID 35682890, 2022). "Here we found that stimulation with 100 ng/ml IGF1 induces more rapid tumor cell migration as evaluated by healing of the scratched area (marked in red)." (PMID 35574343, 2022). "A growing number of reports support that the tumor microenvironment mediates these deleterious effects partly by overexpressing insulin-like growth factor 1 (IGF-1)." (PMID 36017326, 2022). "As prolonged drug treatment will probably be needed to keep IGF1 levels sufficiently low to prevent tumor reappearance or to target longevity, BM001 will be a useful tool to investigate the ancillary factors that affect IGF1 levels." (PMID 35966052, 2022). "IGF-1 interacts with its cognate receptor IGF1R on the surface of tumor cells to activate the phosphatidylinositol 3-kinase (PI3K) signaling pathway, subsequently resulting in tumor resistance and proliferation." (PMID 35600367, 2022). "Among these genes, PLK1, CDC25C, ESCO2, AXIN2, TREX2, ALKBH2, and MC1R were upregulated in tumor tissues, whereas IGF1 and ESR1 presented downregulation." (PMID 35484177, 2022). "The serum IGF1 levels of the tumor bearing GHA mice were suppressed by 88% compared to that in the WT, confirming the attenuation of GH action at a systemic level due to the endogenous GHRA expression." (PMID 35865483, 2022). "As the IGF1R/IGF1 axis is known to prevent tumor cell death, we counted the dead cells in the cell culture." (PMID 35574343, 2022). "Previous studies have shown that IGF-1 can regulate exosome-mediated miRNA transfer and maintain tumor cell proliferation." (PMID 36062186, 2022).
tumor (continued). "The CXCL8 gene showed oncogenic, while IGF1 exhibited tumor suppressor features in tumor fibroblasts." (PMID 36357663, 2022). "PAPPA, a gene involved in IGF-1 signaling, was the most enriched in the stroma compared to the tumor epithelial compartment in ILC." (PMID 35205651, 2022). "Genes from FOS-JUN modules (FOS, JUN, and ERG1), MAPK/ERK, PI3K-AKT and JAK/STAT pathways, and IGF1 involved in tumor growth and resistance to AI, were upregulated in both studies." (PMID 34965950, 2022). "Our results also point to integrins as tumor growth modulators, being related to prior IGF-1 stimulation." (PMID 35053528, 2022). "At the last follow-up, the patient was treated with lanreotide ATG 120.0 mg every 4 weeks in combination with PEGV 240.0 mg/wk; IGF-1 levels and tumor size remained controlled." (PMID 35090028, 2022). "The increased invasive properties of tumor cells after exposure to adipose-derived stroma cells were abrogated by insulin-like growth factor-1 (IGF-1) neutralizing antibodies." (PMID 35435599, 2022). "Subsequently, activated IGF1 signaling further cumulates Wnt/β-catenin activation in atypical PIN cells to promote tumor development." (PMID 35902588, 2022). "qPCR results showed that Pappa, Igf1 and Stc1 were only expressed in the CAFs, while Igf1r, Stc2 and Igfbp4 were expressed in both tumor cells and CAFs." (PMID 35205651, 2022). "In contrast, under pathological conditions, it is well established that IGF-1 functions as a potent mitogen that contributes to tumor progression, increasing metastatic potential and resistance to apoptosis induced by cytotoxic drugs." (PMID 35366286, 2022). "Together, these results suggest that NT157 inhibits cell growth, survival, and migration in vitro, and tumor growth in vivo via inhibiting IGF-1 signaling in UM." (PMID 36551732, 2022). "The IGF1R/IGF1 axis is a crucial progression factor for tumor cell development, supporting tumor cell survival, cell cycle, proliferation as well as cell growth, migration, invasion and angiogenesis." (PMID 35574343, 2022). "IGF1, a polypeptide that contributes to tumor progression, has been reported to be involved in TME status." (PMID 35237505, 2022). "Within the insulin/IGF axis, IGF-1R is capable of stimulating the proliferation and migration of tumor cells through binding with insulin and IGF-1 and activating the downstream tumor-promoting signal pathways." (PMID 35296101, 2022). "Concerning the relation between hepatic expression of IGF-1 protein and the clinico-pathological characteristics of tumor, herein we observed an inverse correlation between hepatic expression of IGF-1 and vascular invasion in HCC patients." (PMID 36374927, 2022). "In a prostate cancer mouse model, calorie restriction decreased tumor weight and plasma insulin levels as well as decreased IGF-1 signaling which was correlated with higher apoptosis levels." (PMID 35796942, 2022). "Taken together, these data uncover a regulatory mechanism by which AR deletion induces IGFBP3 expression in Gli1-lineage FB to block IGF1-signaling activation, further hindering prostatic basal epithelial cell-mediated oncogenesis and tumor development." (PMID 36323713, 2022). "In HCC, the liver tumors overexpress IGF1R, which is now directly fueled by the GH-induced hepatic IGF1 in the tumor milieu." (PMID 35865483, 2022). "SHH from tumor cells in turn induces expression of growth factors insulin growth factor 1 (IGF1) and growth arrest-specific 6 (GAS6) in PSCs." (PMID 35159011, 2022). "Postoperatively, visual field defects were restored, although IGF-1 levels remained elevated and there was a large suprasellar tumor remnant." (PMID 35090028, 2022). "Of note, Insr expression was found upregulated in mouse lungs with compromised IGF1R signaling, and IGF1 expression by the TME was reported to have a supportive role in tumor initiation and progression." (PMID 35688943, 2022).